TLR7 (toll like receptor 7)
Diseases named in the same sentence as TLR7 in open-access papers (continued):
Sharing a sentence is not in itself a finding about the gene and the disease.
melanoma (continued). "Melanoma cells produce immunosuppressive cytokines, such as PGE2, IL-10 and TGF-β, that can inhibit TLR7/9 and IRF7 expression leading to a limited I-IFN production by pDCs." (PMID 32054102, 2020). "In a murine melanoma model, the topical application of IMQ leads to TRAIL and GrB secretion and resulted in tumor clearance in a TLR7/MyD88- and IFNAR1-dependent manner." (PMID 32054102, 2020). "Combination treatment with TLR7 agonist and MEK1/2 inhibitor synergistically improved the survival of a murine melanoma model." (PMID 31507609, 2019). "The melanoma-bearing WT mice were treated with either TLR7 agonist or MEK1/2 inhibitor, or a combination of TLR7 agonist and MEK1/2 inhibitor." (PMID 31507609, 2019). "Melanoma cells produce the immunosuppressive cytokines PGE2, IL-10, and TGF-β, which directly suppress IFN-I production by inhibiting TLR-7/9 and IRF7 expression on pDCs." (PMID 29085361, 2017). "Co-delivery of 3 M-052 (TLR7, TLR8 agonist) and CpG ODN via intratumoral injection has led to complete rejection of large tumors (colon cancer and melanoma) in murine models, while delivery of 3 M-052 or CpG ODN alone only reduced the tumor growth rate." (PMID 25411122, 2014). "This is in contrast with what has been found by others, e.g., co-administration of IMQ and anti-CD40 is ineffective against intradermal B16 melanomas, and required a combination of TLR3, TLR4 and TLR7 stimulation to produce 50% tumor rejection." (PMID 25518732, 2014). "For example TLR7/8 agonists were shown to increase tumor viability and metastasis in lung cancer cells and TLR3 agonists shows proliferation of human melanoma cells." (PMID 23151919, 2012). "In accordance with our in vitro findings that AdjFluVx did not stimulate TLR7, intratumoral administration of AdjFluVx in WT and TLR7-/- mice bearing B16 melanoma tumors did not experience any change in tumor progression." (PMID 38476365, 2024). "Furthermore, our findings showed that combination therapy with anti-PD-L1 antibody and TLR-7/8 agonist also required CD40 positive B cells and their chemokine CXCL13 to generate optimum anti-melanoma immunity." (PMID 35720386, 2022). "Imiquimod (IMQ) is a synthetic ligand of toll-like receptor 7 that exerts antitumor activity and is already topically used in non-melanoma skin cancer and lentigo maligna melanoma in hard-to-treat areas, such as the face." (PMID 36012593, 2022). "Additionally, studies have reported that TLR7 agonist imiquimod augmented the immunogenicity of peptide vaccine by activating the strong and durable response of CD4+ T cells and CD8+ T cells in melanoma." (PMID 35413927, 2022). "The defect in TLR-7 signaling response was not correlated with the melanoma molecular profile in the cohort analyzed herein." (PMID 32731406, 2020). "Combination treatment with MEK1/2 inhibitor and TLR7 agonist did not promote or reduce apoptosis of B16F10 melanoma cells cultured alone." (PMID 31507609, 2019). "As a proof of concept, combination treatment with a TLR7 agonist and MEK1/2 inhibitor synergistically extended the survival of wild-type but not Irf1-deficient melanoma-bearing mice." (PMID 31507609, 2019). "The presence of plasmocytoid dendric cells (pDCs) expressing TLR7 and TLR9 receptors in the inflammatory infiltrate of melanoma metastasis is crucial for treatment with two potent immune stimulators after ECT, such as imiquinod, a TLR7 agonist, and GpG-ODN, a TLR9 agonist." (PMID 26155423, 2015). "Furthermore, we established a subcutaneous B16-F10 melanoma model for intratumoral BCG treatment and compared wild type mice to TLR2-/-, TLR3-/-, TLR4-/-, TLR7-/-, TLR3/7/9-/-, caspase 1-/-, caspase 11-/-, IL-1R-/-, cGAS-/-, STING-/-, IFNAR-/-, MyD88-/-deficient animals." (PMID 38835781, 2024).
melanoma (continued). "TLR7/8 agonist nanoparticles triggered DC activation and expansion, leading to expansion of antigen specific CD8+ T cells and enhanced CTL response, which resulted in significant prophylactic and therapeutic efficacy in melanoma, bladder, and renal cell carcinoma tumor models." (PMID 36476317, 2022). "Melanoma cells have also acquired mechanisms to subvert the immune-stimulatory functions of pDCs, such as secrete immunosuppressive cytokines, including IL-10, TGF-β and PGE2, to suppress the expression level of TLR7/9 and IRF7, resulting in pDCs producing only a small amount of I-IFN." (PMID 34737750, 2021). "Finally, we did not observe TLR3, TLR7 or TLR9 expression in previously published RNA-Seq data of in vitro cultured B16F10 melanoma (data not shown), ruling our direct effects of agonist treatment on the tumor itself." (PMID 34381732, 2021). "In support of an immunogenic pDC role, imiquimod (TLR7 agonist)-mediated regression of melanoma tumors was shown to be dependent on TLR7 expression on pDCs; neither mice lacking TLR7 nor pDC-depleted mice responded to imiquimod therapy and both saw a reduction in apoptosis within treated tumors." (PMID 26042126, 2015). "In conclusion, our study displayed that SZU-101 (a TLR7 agonist synthesized by our group) and JQ-1 (a well-defined BRD4 inhibitor) could be administrated in combination to achieve better repressive effects on tumor growth and metastasis in both murine breast cancer and melanoma models." (PMID 38203835, 2024). "We validatedthis result with a similar experiment in B16F10 melanoma, where wecompared p(Man-TLR7-PDS) to nonbinding p(Man-TLR7) and observed atrend toward reduced cytokine levels." (PMID 36313164, 2022).
basal cell carcinoma (42 papers, 2007 to 2025). A carcinoma involving the basal cells. "The TLR7 agonist imiquimod has been used successfully as adjuvant for skin treatment of virus-associated warts and basal cell carcinoma." (PMID 22927956, 2012). "Among the CXCL chemokines, CXCL-12/SDF-1 was previously associated with the rejection of metastatic melanoma during IL-2 therapy and together with CXCL-9 through -11 chemokines in association with the rejection of basal cell carcinomas (BCCs) treated with TLR7 agonists." (PMID 19583830, 2009). "Imiquimod, a famous TLR7 agonist, is approved for the topical treatment of superficial basal cell carcinoma." (PMID 38605368, 2024). "The approved therapeutics are duvelisib, a PI3Kγ and PI3Kδ inhibitor for haematological malignancies, and imiquimod, a toll-like receptor 7 (TLR7) agonist for topical treatment of basal cell carcinoma." (PMID 38831013, 2024). "The TLR7 agonist imiquimod is routinely used for the topical treatment of basal cell carcinoma and a wide range of TLR agonists are explored in clinical trials for cancer treatment." (PMID 36913398, 2023). "Imiquimod, is a synthetic imiquinolin connected to TLR7 and used to treat some cancers including surface basal cell carcinoma and its purity degree reported from 79% to 82%." (PMID 31673257, 2019). "Imiquimod is a topical toll-like-receptor-7 agonist currently used for treating basal cell carcinoma." (PMID 31189943, 2019). "The use of Imiquimod in the treatment of superficial basal cell carcinoma and other skin conditions is based on the ability of this molecule to activate TLR7 and thus exert an increase in inflammatory cytokines and type I IFNs23–25." (PMID 29973684, 2018). "Imiquimod is FDA approved as a topical cream for the treatment of superficial basal cell carcinoma, external genital warts and actinic keratinosis, where its mechanism of action is to orchestrate a pro-inflammatory response through TLR7." (PMID 29973684, 2018). "In chronic lymphatic leukemia and basal cell carcinoma, TLR7 and -8 agonists of both natural (e.g., single stranded RNA, ssRNA) and synthetic (e.g., Imiquimod) origin have demonstrated promising antitumor activity." (PMID 27941651, 2016). "The TLR7/8 agonist R837 is used for the topical treatment of genital warts, basal cell carcinoma, and bladder cancer." (PMID 26770023, 2015). "This study was part of a placebo-controlled double-blind clinical trial in which basal cell carcinomas were treated topically with an immunomodifier – toll-like receptor 7 agonist: imiquimod." (PMID 17313672, 2007). "Samples were obtained as part of a placebo-controlled double-blind study of gene expression profiling of basal cell carcinoma treated topically with Imiquimod, a drug whose activity is mediated through toll-like receptor 7 (TLR-7) signaling." (PMID 17313672, 2007). "In addition, TRAIL+ pDC infiltration is observed in basal cell carcinoma lesions treated with the topical TLR7 agonist IMQ, suggesting that TLR-activated pDCs contribute to rejection of cutaneous tumors." (PMID 32054102, 2020). "Furthermore, TLR7 agonists such as FDA-approved imiquimod has been used in the treatment of superficial basal cell carcinomas (sBCCs) and dermatological malignancies, with complete tumor clearance after just 6 weeks of treatment with no recurrence." (PMID 31835892, 2019). "Imiquimod, a ligand for TLR7 and TLR8, is a potent immune activator also used for the treatment of virus-associated skin abnormalities as well as (pre)cancerous skin lesions and superficial basal cell carcinomas." (PMID 30613363, 2018). "The TLR7 agonist imiquimod, approved by the FDA for squamous and basal cell carcinoma via topical application, and the TLR7/8 agonist resiquimod are also being tested in GB, but less so than Hiltonol." (PMID 40642066, 2025).
basal cell carcinoma (continued). "Because they can mediate the anti-tumor effect, TLR agonists such as imiquimod, which activates TLR7/8 pathways, have been approved by the U.S. Food and Drug Administration (FDA) to treat patients with basal cell carcinomas." (PMID 38256021, 2024). "Currently, imiquimod (TLR7 agonist) is permitted by the FDA for topical application in squamous cell carcinoma and basal cell carcinoma." (PMID 39065562, 2024). "Imiquimod is one of the most studied TLR7 agonists, approved by the FDA for the treatment of superficial skin cancers such as basal cell carcinoma." (PMID 39451226, 2024). "IMQ is an agonist of TLR7 and TLR8 and is approved for the treatment of genital warts, superficial basal cell carcinoma, and actinic keratosis." (PMID 35116069, 2022). "Imiquimod is a TLR7 (and TLR8 in humans) agonist used for the treatment of superficial basal cell carcinomas, actinic keratoses and some viral skin infections." (PMID 36477177, 2022). "IMQ is an agonist of the toll-like receptor-7/8 (TLR-7/8) which has been approved for the treatment of actinic keratosis, external genital warts, and superficial basal cell carcinoma." (PMID 29619073, 2018). "Imiquimod (IMQ), a synthetic toll-like receptor 7 (TLR-7) agonist is an FDA-approved immunotherapy drug which used in actinic keratosis, basal cell carcinoma, and Bowen’s disease treatment." (PMID 30970893, 2017). "Imiquimod (IMQ) is an agonist of toll-like receptor-7/8 (TLR-7/8), which is widely used to treat condyloma acuminata, solar keratosis and basal cell carcinoma." (PMID 27581210, 2016). "Despite tremendous efforts, only imiquimod (Aldara), a TLR7 agonist, has been approved by US FDA for treatment of papillomavirus-induced genital warts and basal cell carcinoma via topical use." (PMID 23056170, 2012). "Toll-like receptor 7/8 (TLR7/8) agonists, such as imiquimod (IMQ), with topical applications (e.g., 5% cream) have already been used in the clinic for treating various localized cancers (e.g., basal cell carcinoma)." (PMID 40547481, 2025). "Notably, the TLR7 agonist imiquimod is used to treat basal cell carcinoma and encouraging results have been observed by simultaneously targeting TLR3 and TLR7." (PMID 38476365, 2024). "Targeting of TLR3, TLR7, TLR8, and TLR9 have all been evaluated in the past few years but currently, a TLR7 agonist, imiquimod, is the only FDA-approved, topical-only treatment for squamous and basal cell carcinomas." (PMID 34209703, 2021). "In this perspective article we highlight recent findings showing that the Toll-like receptor-7/8 (TLR7/8) agonist imiquimod (IMQ), an immune modulator approved for the treatment of basal cell carcinoma, can also act as a potent cell autonomous inhibitor of oncogenic HH signaling." (PMID 25594066, 2014). "On the other hand, there is not enough evidence to determine the utility of TLR7/8 as a target for a vaccine adjuvant despite that the TLR7 agonist imiquimod has been licensed as a topical formulation to treat genital warts, actinic keratosis, basal cell carcinoma, and lentigo maligna." (PMID 25875128, 2015). "Imiquimod (IMQ) is a synthetic TLR7 agonist approved by the FDA for the treatment of non-melanoma skin cancers (e.g., basal cell carcinoma)." (PMID 32054102, 2020).
lung carcinoma (41 papers, 2012 to 2025). "TLR7 was also reported to be tightly associated with the prognosis of non‐small cell lung cancer by facilitating tumor progression and reducing chemosensitivity." (PMID 33982398, 2021). "The activation of TLR7–IFN signaling in lung cancer cells leads to an increase in the secretion of chemokine CXCL10, which contributes to immune cell infiltration." (PMID 40727252, 2025). "By upregulating pro-inflammatory cytokines, anti-apoptotic protein Bcl-2, and angiogenesis-related VEGFR2, TLR7 activation in lung cancer increases tumor cell survival and resistance to apoptosis." (PMID 38850110, 2024). "In a murine model of lung carcinoma, tumor cells activated through TLR7 are able to recruit myeloid-derived suppressor cells (MDSCs) via the release of cytokines such as CCL2 and GM-CSF." (PMID 37207158, 2023). "By contrast, several studies have shown that TLR7 is highly expressed in lung cancer cells, leading to increased tumor cell survival, chemoresistance, and poor clinical outcomes." (PMID 36793597, 2023). "In a lung cancer mouse model, TLR7 stimulation with R848 induced DC activation, increased CD8+ T and NK cells and decreased Treg cells." (PMID 37112730, 2023). "Engagements of TLR7 or TLR8 agonists in lung cancer cells can induce the activation of NF-κB and upregulation of Bcl-2 expression, leading to increases in cell survival and resistance to apoptosis." (PMID 37443143, 2023). "Exosomal miR-21 and miR-29a from lung cancer cells activate mouse TLR7- and human TLR8-mediated NF-κB activation in immune cells and the production of proinflammatory IL-6 and TNF-α to promote lung cancer and metastasis in mice." (PMID 35562884, 2022). "High TLR7 expression in the primary tumor confers poor clinical outcome and resistance to chemotherapy in lung cancer patients." (PMID 36476317, 2022). "A preclinical study showed that TLR7 agonists inhibit the growth and metastasis of lung cancer cells through immune activated mesenchymal stem cells." (PMID 36476317, 2022). "Our data indicate that TLR7 sustains a pro-resolving signaling in lung cancer that inhibits angiogenesis." (PMID 33578955, 2021). "It was shown that sEV delivered miR-29b and miR-21 can bind and activate toll-like receptor 7/8 (TLR7/8) in human lung cancer." (PMID 33154755, 2020). "For example, lung cancer cells activate Toll‐like receptors TLR7 and TLR8 on immune cells via exosomal miR‐21 and miR‐29a, leading to tumour growth and metastasis." (PMID 32391938, 2020). "For example, miRNAs were identified as capable to activate toll-like receptors, promoting inflammatory responses in lung cancer by miR-21 and miR-29a and neurodegeneration by let-7 activations of TLR7." (PMID 31540501, 2019). "In lung cancer, TLR7 and TLR8 signaling promoted cell proliferation and chemoresistance and was associated with the poor survival of patients." (PMID 27248820, 2016). "Stimulation with TLR7 agonists on human lung cancer cells has been shown to lead to increased tumor cell survival and chemoresistance." (PMID 23451142, 2013). "MicroRNA-574-5p of extracellular vesicle origin regulates prostaglandin E2 biosynthesis through activation of TLR7/8, which in turn affects the communication process between lung cancer cells.TLR pathway has emerged as a promising therapeutic strategy for lung cancer." (PMID 40166469, 2025). "In cancer, TLR7/8 have been shown to be expressed in lung cancer, colorectal cancer and PDAC." (PMID 37112730, 2023). "In addition, exosomal miR-21/29a released by lung cancer cells activates TLR7 and TLR8 on macrophages triggering the NF-kB pathway and release of inflammatory cytokines that sustain tumor growth and metastasis." (PMID 37207158, 2023). "In addition, the TLR7/8 agonist R848 optimizes host and tumor immunity to improve therapeutic efficacy in murine lung cancer." (PMID 36476317, 2022). "This pro-tumorigenic effect of TLR7 has been validated in murine models of lung carcinoma." (PMID 36476317, 2022).